IL6 (interleukin 6)
Diseases named in the same sentence as IL6 in open-access papers (continued):
Sharing a sentence is not in itself a finding about the gene and the disease.
infection (continued). "Challenges to routinely measuring IL-6 include absence of an agreed “normal” range, variability due to trauma, infection, age, and vascular co-morbidities, and sensitivity to sample processing factors such as delay to analysis and temperature." (PMID 41541100, 2023). "We thus identified several alternative inflammatory genes whose expression was either completely (Cxcl1) or partially (Ccl2 and Il6) independent of IFNAR1 signaling following infection." (PMID 38011306, 2023). "Plasma cytokines (IL-1β, IL-3, IL-6, IL-8, IL-18, IP-10, MIG, TNF-α, IFN-γ, MIP-1α and MIP-1β) and total peroxide (TPX) levels were quantified at baseline and at months 1 and 6 after the onset of the infection." (PMID 37894054, 2023). "In the early stages of infection, TNF-α and IL-6 can activate neutrophils, and the more rapid lytic activity of lysins may lead to more peptidoglycan fragments, which provoke severe proinflammatory reactions." (PMID 37125939, 2023). "Even against the pathogen infection, the precise mechanism of action of BOT appears to be directed towards the modulation of the epithelial inflammatory response: the reduced expression of TNFα and IL-6 are indicators of a decreased inflammatory tone." (PMID 37841479, 2023). "Hence, immunofluorescence staining of IL-6 and TNF-α was performed to evaluate the infection levels and healing status of the wounds." (PMID 36696504, 2023). "The study’s results showed that PTX3 facilitated the phagocytosis of macrophage Ana-1 against SS2 strain HA9801, and contributed to inflammatory cell recruitment and cytokine IL-6 release in the mouse air pouch; thus, it was conductive to bacterial clearance during the SS2 infection." (PMID 36977278, 2023). "Indeed, several inflammatory mediators influence haemostatic mechanisms, namely interleukin 1 (IL-1), interleukin 6 (IL-6) and tumour necrosis factor-alpha (TNF-α), which are synthesized during innate immune response upon infection." (PMID 36617364, 2023). "Trim32−/− mice had a lower bacterial burden after Lm infection and survived significantly longer than wild-type (WT) mice, as well as lower serum levels of inflammatory cytokines TNF-α, IL-6, IL-18, IL-12p70, IFN-β, and IFN-γ at 1 day post infection (dpi) compared to WT mice." (PMID 37415157, 2023). "Furthermore, Mtb also increases IL-6 production in infected macrophages, reducing IFN-γ effector signaling and contributing to an impaired cellular immune response and impaired infection eradication." (PMID 37892223, 2023). "Increased production of IL-6 from fetomaternal tissue in response to infection is a nonspecific innate response and is an indicator of adverse pregnancy outcomes." (PMID 37384100, 2023). "CRP, and PCT are examples of these proteins, the synthesis of which in hepatocytes is stimulated by the action of pro-inflammatory cytokines (among others, IL-6, IL-1β, and TNF-α) in inflammation or tissue damage; they are used globally as a marker of inflammations and infections." (PMID 37509519, 2023). "Our study population was highly selected since the subjects had failed on corticosteroids and that IL-6-blocking regimens such as TCZ were considered inappropriate due to a lack of CRP reaction in case of an infection." (PMID 37304255, 2023). "During an infection caused by Gram-negative bacteria, the synthesis of proinflammatory cytokines such as TNF-α and IL-1, IL-6, IL-8, and IL-10 is also more frequent." (PMID 37762882, 2023). "Subsequently, we examined whether IL-6 signalling could confound observational estimates between HDL subclass particle counts and infection." (PMID 37814277, 2023). "GO analysis of the infection genes upregulated at one week indicated processes involved in immune responses and cytokine production, including responses to interferon-gamma and positive regulation of TNF, IL6, and IL1β production." (PMID 37200402, 2023).
infection (continued). "Notably, the levels of IL-1β, IL-6, and TNF-α were significantly elevated following infection with B1033 compared with those in the wild-type (p < 0.001)." (PMID 37998345, 2023). "Simple stimulation of IMR-90s with TNF-α without infection (MOCKTNF-α) did not result in upregulation of the factors IL-6, IL-8, and IP-10 at mRNA level." (PMID 37163429, 2023). "For instance, over the 72-h period following infection, IL-6 secretion was comparable for AUD and non-AUD cells, although AUD cells had an earlier IL-6 response than non-AUD cells." (PMID 37786945, 2023). "Moreover, serum IL-6 and IL-10 in the GN-BSI group sharply increased within 6 h post-infection, reaching peak levels around 6 h, and then gradually decreased to their original levels within 48 h." (PMID 37986183, 2023). "Concerning IL-6, the reconstitution of Gx mice with DHEA without infection increased IL-6 concentrations in both sexes." (PMID 37628731, 2023). "Furthermore, the infection also encourages macrophages to secrete pro- and anti-inflammatory cytokines such as tumor necrosis factor-α (TNF-α), interleukin-1β (IL-1β), IL-6, interferon-γ (IFN-γ) and IL-10." (PMID 37280772, 2023). "In bovine macrophages, oxygen availability neither influenced the expression level of IL-6 nor that of the at 24 and 96 h post-infection." (PMID 36793725, 2023). "Similarly, the expression levels of pro-inflammatory response factors (IL-6, TNF-α, CXCL10, CCL7, CXCL11, and CCL2) were significantly decreased at 6 dpi, as compared to virulent WT infection." (PMID 37623322, 2023). "In the study of infection in non-pregnant women, the virus increased certain cytokine levels, such as IL-6, IL-2, and IFN-g." (PMID 37376620, 2023). "By contrast, cells that were pretreated with chloroquine before infection exhibited trends towards decreasing levels of proinflammatory TNF-α, IL-6 and IFN-γ, and increasing levels of IL-1β, compared with untreated cells infected with Mel+ or Mel˗ S. globosa conidia." (PMID 37141335, 2023). "As expected, infection significantly induced IL-1β, TNF-α and IL-6 placental secretion." (PMID 36982317, 2023). "In addition to early events in the lung during Δpla infection, expression of IL-6, IL-17, and MCP-1 has been previously shown to correlate with levels of pulmonary neutrophils during the later proinflammatory stage of infection." (PMID 37338372, 2023). "As we previously reported that the infection of macrophages is closely related to their inflammatory state, we investigated the expression of three inflammatory cytokines, TNF, IL1 and IL6, and one immunoregulatory cytokine, IL10, by MDMs and PMs infected with C. burnetii using qRT-PCR." (PMID 36674725, 2023). "The examination of human cytokine levels revealed that while the levels at the primary site of infection were similar for huSGM3 and huNSG mice, strongly increased levels of CCL2, IL-6, IL-8 and TNF-α could be measured by the Luminex assay in the blood." (PMID 36969151, 2023). "At 12 h post-infection, THP-1 macrophages secreted higher levels of TNF-α, IL-6, IL-1β and IFN-γ compared with untreated/uninfected controls, with the Mel˗ conidia group showing significantly higher levels of all four factors compared with the Mel+ conidia group (P < 0.05)." (PMID 37141335, 2023). "Given that DMI suppresses IL-6 and IL-10 and induces autophagy in macrophages during infection, we evaluated its effect on the activation of the transcription factor STAT3, which modulates gene expression in response to IL-6 and IL-10 and the suppression of autophagy." (PMID 36882813, 2023). "Recombinant IL-6 cytokine did not increase infection in activated CD4 + T cells by itself, nor did the anti-IL-6 antibody interfere with IEC stimulation." (PMID 37202790, 2023).
infection (continued). "Whole lung tissue was collected 24 h after infection and processed for RT-qPCR to evaluate for relative gene expression of proinflammatory genes IRAK1, TRAF6, NF-κB, IL-6, MIP-2 (murine IL-8 analog), IL-1β, and TNFα as these cytokines outline the pathway along which miR146a functions." (PMID 37765178, 2023). "SARS-CoV-1 nucleocapsid protein can stimulate NF-κB activation and IL-6 production independent of infection." (PMID 37552656, 2023). "No infection by Salmonella was performed in this model but a stimulation with Salmonella LPS revealed the possible induction of an innate immune response with IL-6 and IL-8 increased expression 6 h after stimulation." (PMID 37525204, 2023). "Low dose challenge, regardless of the mode of infection, was not sufficient to induce IL-6 release at the time points evaluated." (PMID 37917623, 2023). "Importantly, the induction kinetics of IL-6 and CXCL8 post-infection are consistent at the mRNA and protein levels in our study, which further strengthens the robustness of our data." (PMID 37112842, 2023). "Moreover, the expression of immune-related genes (SAA, iNOS, IL-1 β, IL-6, IL-10, TNF α, C3, MHC I, MHC II, CD4, CD8, TCR α, IgM, IgD and IgZ) increased in all groups post infection, which was more significant in the vaccinated groups." (PMID 36969197, 2023). "No detectable levels of IFN-γ and IL-6 were found during the chronic phase of the infection (90 days p.i.)." (PMID 37691941, 2023). "Infection increased serum IL-6 and IFN-γ and tissue caspase-1 but not NLRP3 in P2X7−/− mice compared to WT mice." (PMID 36831091, 2023). "To determine whether OI-14-15 regulates noncanonical inflammasome activation directly or by manipulating the TLR-dependent IFN or pro-IL-1β synthesis, we assessed the levels of IFNβ and pro-IL-1β as well as IL-6 and TNF at early stages of infection." (PMID 37041208, 2023). "In our model, however, there is acquired immunodeficiency, which compromises adaptive immunity, thus chronifying the innate immune response with continued release of proinflammatory cytokines (IL-6, TNFα, and IFN-γ) and preventing the infection from ever resolving." (PMID 37718435, 2023). "When PBC patients were exposed to LPS due to infection, LPS could bind to cell surface receptors (such as TLR 4/CD14) and induced the secretion of pro-inflammatory cytokines (such as TNF-α, IL-1, IL-6, IL-8), promoting inflammation." (PMID 38111586, 2023). "The treatment with TNF-α without infection (MOCKTNF-α) did not result in the upregulation of IL-6, IL-8, and IP-10 on mRNA level at either 8 h or 24 h." (PMID 37163429, 2023). "The results showed that the protein concentration of inflammatory cytokines in both types of mice was significantly increased after BMA8 strain infection, and the expression of cytokines was higher in BALB/c mice, including IL-2, IL-4, IL-6, IL-10, IL-12p70, KC/GRO, IFN-γ and TNF-α." (PMID 37081549, 2023). "CRP is a non-specific acute phase protein, induced by IL-6 in the liver, and is a sensitive biomarker of inflammation, infection, and tissue damage." (PMID 37373750, 2023). "Therefore, IL-6 can serve as an early marker for identifying EOS and mild infections, offering a means to predict the subsequent elevation in CRP levels." (PMID 38255366, 2023). "Similarly, on day 7 after infection, the levels of TNF-α, IL-6, and IL-10 were higher in ΔPbMAP1-infected mice." (PMID 37563696, 2023). "BARM showed a more inhibitory effect compared to the control at 18 h post-infection with IL-6 and IL-8 but not for IL-1β." (PMID 36992362, 2023). "In the draining lymphatics, except for modest but significant differences in IL-6 and KC, concentrations of cytokines were similar regardless of the route of infection." (PMID 37883420, 2023).
infection (continued). "To confirm that IL6 expression impairs liver stage development of transgenic parasites, we examined by fluorescence microscopy EEF in the liver of mice harvested 24h or 40h after infection with 5 x 104 WT PbA or IL-6 Tg-PbANKA/LISP2 SPZ." (PMID 37143657, 2023). "Finally, another study has shown that patients with respiratory symptoms of LC exhibited higher levels of CRP, IL-6 and SARS-CoV-2-CD4+/CD8+ T cells secreting IFN-γ or TNF-α at 7-months post-infection." (PMID 37445634, 2023). "Infection with the H7N7 resulted in increased levels of CCL2, IFNγ, IL1β, IL-6, and TNFα in the brains of mice, whether or not they had been previously vaccinated." (PMID 37063291, 2023). "At 18 h post-infection, NSC exerted inhibitory activity only on IL-6." (PMID 36992362, 2023). "As inflammatory cytokines (IL-1, IL-6, IL-8, TNF-α) are induced by the infection of CF lungs, additional studies, e.g., bulk RNA sequencing, may reveal new inflammatory pathways that are upregulated by P. aeruginosa during prolonged infection of HBE." (PMID 37998353, 2023). "Upregulation of IL-6 and OSM may also be explained by increased fibroblast activity dependent on ongoing chronic local inflammation possibly initiated by infection." (PMID 37047067, 2023). "Interleukin-6 (IL-6) is one of the cytokines involved in SARS-CoV-2-induced inflammatory response and monoclonal antibodies against the interleukin-6 receptor (IL-6R)—namely tocilizumab (TCZ) and sarilumab (SAR)—have been used in severe infection." (PMID 37218940, 2023). "In addition, myristic acid treatment decreased HSV-1-infection- and ISD-induced the expression of tumor necrosis factor-α (Tnfa), and interleukin-6 (Il6)." (PMID 36750575, 2023). "Furthermore, significant variations were observed in the levels of IFNL1, IL1A, IL6, and CCL2 interferons or other cytokines in cell supernatant through ELISA when comparing these two infection conditions." (PMID 37515115, 2023). "Similar IL-6 levels were found for group 1 (EOS) and group 2 (mild infection)." (PMID 38255366, 2023). "In patients with infection-related ARDS, it was found that both serum and BALF levels of sRAGE were much higher than those in control subjects, and they were positively correlated with levels of IL-6 and IL-8, which was consistent with our findings." (PMID 36691012, 2023). "Infection with all three strains (HN878, rpoB-S450L, and rpoB-H445Y) resulted in increased production of other cytokines that were measured, such as the pro-inflammatory IL-6 and the anti-inflammatory IL-10." (PMID 37682004, 2023). "For both IL-6 and CD2 blocking, the antibody was refreshed 1-day post-infection." (PMID 37202790, 2023). "In all these previous studies IL-6 or CRP were not measured during infection, but at a fixed timepoint during pregnancy." (PMID 37789021, 2023). "For example, immunological signatures are altered during severe infection, and levels of a wide range of pro-inflammatory cytokines [such as S100A8/A9, interleukin 1 beta, interleukin 6 (IL-6), IL-8, CXCL10, and tumor necrosis factor alpha (TNFα)] are dramatically increased." (PMID 37936693, 2023). "In exercise settings, IL-6 is not preceded by an increase in plasma TNF-alpha as seen during infections." (PMID 37312098, 2023). "After intratracheal infection with Pseudomonas aeruginosa, KO mice showed increased mortality, higher injury scores, more severe inflammation in the lung and kidney, and increased serum TNF-α, IL-1β, and IL-6 levels compared to WT and hTG mice." (PMID 37256132, 2023). "In our institution, however, no routine IL-6 measurements are performed; therefore, every patient in this study had at least at one point a suspected infection leading the providing clinician to order a blood sample." (PMID 36216867, 2023). "Moreover, DMI markedly suppressed IL-6 and IL-10 production in BMDMs infected with Mtb, BCG, or Mav, compared with those induced by the infection alone." (PMID 36882813, 2023).
infection (continued). "At 6hours after FMDV infection, transcription levels of IFN-β and IL-6 were detected." (PMID 37565750, 2023). "Consistent with SARS-CoV-2 infection of human airway epithelial cells, we observe a rapid proinflammatory response during the early stages (24 h) of infection characterized by an increased expression of multiple cytokines and chemokines (e.g., CCL20, IL-6, CXCL8 and CXCL10)." (PMID 37112842, 2023). "In the present study, expression of inflammatory cytokines (IL-1 β, IL-6, IL-10, TNF α and iNOS) and acute phase protein SAA were up-regulated post infection, especially that of the vaccines immunized groups, indicating that vaccination promoted host innate immunity of M. amblycephala." (PMID 36969197, 2023). "CXCL-10, IL-6, G-CSF, MCP-1, TGF-a, TNF-a, MIP-2-A, BAFF, MDC, TRAIL-R2 and MIP-1-A all had at least 2-fold change from mock-infected wells, although many proteins in the panel showed some degree of upregulation post-infection." (PMID 37766362, 2023). "Other inflammatory makers, including IL-1α, IL-1β and IL-6, were not different between infection groups." (PMID 36748431, 2023). "We previously showed that the N protein produced in infected epithelial cells can induce IL-6 production via myeloid cells and macrophages without direct infection with SARS-CoV-2." (PMID 37896795, 2023). "We report that during infection of macrophages and dendritic cells with various intracellular bacteria, XIAP restricts cell death and secretion of IL-1β but promotes increased activation of NFκB and JNK which results in elevated secretion of IL-6 and IL-10." (PMID 37347786, 2023). "IL-6 was markedly increased in infected cancer patients (P <0.01) but remained at a low level and had no apparent change during the whole infection process in non-cancer-afflicted subjects." (PMID 37035158, 2023). "Infection of PBECs led to induction of CXCL8, interleukin (IL)-1β, IL-6 and TNF." (PMID 37180449, 2023). "We previously observed that the essentiality of IL-6 is variable during infections by different clones of GAS, unlike what was observed with IL-1, which has an invariant role in immunity between GAS strains." (PMID 37874162, 2023). "Regarding infection by SARS-CoV-2, it was possible to assess that the role of melatonin can be related to the control of inflammation, since there was a correlation between the increase in this hormone and the increase in IL-6." (PMID 37239991, 2023). "In contrast, the infected control group had 60.2 ng/mL, 2.3 ng/mL, 1,073.9 ng/mL, and 532.2 ng/mL levels of IL-6, TNF-α, KC, and CRP, respectively, in the 5th h after infection, and these levels decreased by 18.5, 2.3, 10.5, and 8.4 times at the 8th h, respectively." (PMID 37293234, 2023). "Besides the positive effects of MCs in fighting infections, on the other hand, viruses stimulate mucosa MCs to release pro-inflammatory cytokines such as IL-1, TNF, IL-6, and proteases which aggravate the inflammatory state." (PMID 37515272, 2023). "One showed potential clinical signs but lacked laboratory evidence of infection, while the other displayed no clinical symptoms but had an elevated interleukin 6 level at 321 pg/mL as the singular laboratory sign." (PMID 38002900, 2023). "Following the initial infection of the lungs by SARS-CoV-2, a cytokine storm is generated, characterized by the release of various cytokines such as tumor necrosis factor-alpha (TNFα), interleukin-1β (IL-1β), and IL-6." (PMID 38162133, 2023). "Independent of infection, bronchial epithelial cells from obese subjects showed a higher IL-6 expression at 4 h than the bronchial epithelial cells from non-obese subjects." (PMID 37047702, 2023). "Interestingly, POPG failed to inhibit RV-A16 replication even though it attenuated virus-induced IL-6 and CXCL11 secretion at 48 h post-infection." (PMID 36992456, 2023). "Generally, the determination of cytokines a few hours after infection initiation reveals high IL-6 values, whereas TNF is no longer detectable." (PMID 37627653, 2023).